CAV1 (caveolin 1)
Diseases named in the same sentence as CAV1 in open-access papers (continued):
Sharing a sentence is not in itself a finding about the gene and the disease.
tumor (continued). "In fact, different CAV1-based anticancer therapies have been proposed for several tumor types." (PMID 39339236, 2024). "Sequencing data from the primary tumor shows that knocking out Cav-1 affects the expression of several epithelial migration genes, which might contribute to lung metastasis." (PMID 39244591, 2024). "In further analysis, high CAV1 gene expression was associated with a molecular profile indicating altered metabolism, neovascularization, chemoresistance, EMT, suppressed immune response, and active tumor microenvironment." (PMID 38959243, 2024). "As an important mechanical signal-sensitive molecule, Cav-1 could respond to mechanical factors from the tumor microenvironment and regulate cell behavior through a series of molecular signal responses." (PMID 39318372, 2024). "We then performed further studies to investigate the role of Cav-1 in tumor cell invasion in vivo." (PMID 39318372, 2024). "Furthermore, tumor tissues with Cav-1 silence showed lower positive area and nuclear translocation of YAP." (PMID 39318372, 2024). "We first constructed an in vivo tumor model by injecting BC cells into the mammary fat pads of mice and then domesticated the lung tissues by injecting BC cell-derived sEVs with different levels of CAV1 into the tail vein." (PMID 39494337, 2024). "Higher expression levels of CAV1 may increase the invasiveness and migration of tumor cells, accelerating tumor progression and worsening patient outcomes." (PMID 39364312, 2024). "Besides NF2, the same study found that several other tumor suppressors, including OPCML, Cav-1, and UGT2B17, showed a loss of tumor suppressive effects." (PMID 39796693, 2024). "Ago2/CAV1 interaction plays a role in miRNA-mediated mRNA suppression and in miRNA release via extracellular vesicles (EVs) from tumors into the circulation, which can be used as a biomarker of tumor progression." (PMID 38649663, 2024). "In addition, blocking Ago2/CAV1 interaction in HCC1806Ago2-KO/AID-Ago2Wt/Ago2∆ cells decreased primary tumor cell dissemination to lymph nodes by 86% (Fig. 5Fiii) and to the lungs by 84% (Fig. 5Fiv)." (PMID 38649663, 2024). "Tumor samples from lovastatin-treated mice were characterized by reduced cellular necrosis, the disappearance of Cav-1, a CHO binding protein that exerts a pro-tumorigenic role in RMS, and by the reduction of pAkt1, indicating that lovastatin-treated tumors were characterized by reduced malignancy." (PMID 39706565, 2024). "We next investigated whether blockage of Ago2/CAV1 interaction affects the metastatic tumor formation of circulating cancer cells in organs." (PMID 38649663, 2024). "In EWS tumor, EphA2 interacts with CAV1 through a caveolin binding motif (WSYGIVMW)." (PMID 39596256, 2024). "Furthermore, CAV1 is linked to angiogenesis, endothelial permeability, and vascular endothelial growth factor (VEGF) response, which is required for tumor survival and the ability to enter the circulation." (PMID 38509243, 2024). "Additionally, CAV1 expression confers a proliferative advantage in lung adenocarcinoma cells, fostering increased tumour aggressiveness." (PMID 38158643, 2024). "Assessment of CAV1 expression in tumor samples from previous randomized clinical trials is warranted to confirm whether CAV1 expression may further refine ROR score prediction." (PMID 38509243, 2024). "Tumor tissue microarrays were used to evaluate CAV1 protein levels in stromal and malignant cells." (PMID 38959243, 2024). "Additionally, the efficacy of peptides based on the CAV1 scaffolding domain (82DGIWKASFTTFTVTKYWFYR101) in impairing in vitro cancer cell migration and delaying in vivo tumor progression were reported." (PMID 39339236, 2024). "The role of CAV1 in tumor development is intricate and controversial." (PMID 39596307, 2024). "A similar effect of reduced caveolin-1 has been documented in some tumor types." (PMID 38067108, 2023).
tumor (continued). "Additionally, tumor-specific CAV1 data were available, enabling a unique dataset with long-term follow-up for analysis." (PMID 37017811, 2023). "Recent data support the high level of versatility of the technique, with the identification of a series of housekeeping proteins, such as Rab5b, CD81, and CD63, and tumor-specific markers, such as PSA, but also surrogate tumor markers, such as Cav-1 and carbonic anhydrase." (PMID 37296842, 2023). "Beyond existing tumor-related prognostic factors, CAV1 genotypes might offer new prognostic information related to the host." (PMID 37017811, 2023). "Another study reported that ROS produced by tumor cells reduced CAV1 expression in CAFs." (PMID 38234683, 2023). "The increased migration and invasion ability of invasive MDA-MB-231 cells and noninvasive MCF-7 cells at the high expression level of the Cav-1 group suggested that Cav-1 in tumor-derived exosomes could promote BC metastasis." (PMID 37056561, 2023). "Here, we evaluated whether exposure to PGE2 sufficed to unleash the tumor-promoting role of CAV1, even in the presence of E-cad, and found that this was indeed the case, without the need for E-cad downregulation." (PMID 38069269, 2023). "The extent to which Src-mediated phosphorylation of CAV1 modifies Kv1.3-related tumor progression is unknown." (PMID 37345053, 2023). "Thus, PGE2 dissociates the CAV1/E-cad tumor suppressor complex to promote its own production (positive feedback loop) as well as metastasis via CAV1 release and enhanced Y14 phosphorylation." (PMID 38069269, 2023). "Through in vitro experiments, we further observed that the detrimental outcomes of ROS on tumor vascular normalization could be mediated through an endocytosis of the caveolin-1 on extracellular SPARC." (PMID 37528424, 2023). "Thus, PGE2 exposure to cells overrides the tumor suppressor capacity of the CAV1/E-cad complex and releases CAV1 to promote metastasis." (PMID 38069269, 2023). "Cav-1 plays an important regulatory role in tumor invasion and migration." (PMID 37828916, 2023). "Finally, expression of two known as tumor suppressor genes, Cav1 (caveolin 1) and Wif1 (wingless-type inhibitory factor-1) was examined." (PMID 37513116, 2023). "The tumor-suppressive properties of Cav-1 expressed in CAFs can be achieved via several mechanisms." (PMID 37143134, 2023). "Additionally, tumor suppression was enhanced when E-cad was co-expressed with CAV1 in B16F10 (CAV1/E-cad) cells." (PMID 38069269, 2023). "Although CAV1 has been extensively described to play an oncogenic role—in fact, it was the first described Src substrate correlated with cell transformation—CAV1 also shows tumor suppressor activity." (PMID 37345053, 2023). "Interestingly, Cav1 in stromal cells has been also reported to promote tumor invasion and metastasis through the modification of the ECM." (PMID 36980283, 2023). "The tumor delivery of nab-paclitaxel has been thought to be an active process, through which the nanoparticles can bind gp60 expressed on the tumor vascular endothelium facilitating caveolin-1-mediated transcytosis." (PMID 36839841, 2023). "However, the degree of CAV1 membrane positivity was heterogeneous across tumors; in some tumors, CAV1 membrane positivity was observed throughout the tumor, whereas in other tumors, it was observed only in limited areas." (PMID 37047005, 2023). "This further suggests a putative tumor suppressor role of caveolin-1." (PMID 36869937, 2023). "Although many studies concentrated on the function of Cav-1 as an intracellular protein, only a few studies have indicated that Cav-1 may be transported by exosomes and promote tumor metastasis by helping PMN formation." (PMID 37056561, 2023). "In addition, CAV1 expression can directly or indirectly promote tumor multidrug resistance and affect the interaction of tumor cells with the mesenchymal microenvironment." (PMID 37907864, 2023).
tumor (continued). "Cav1 has tumor suppressive and radioresistant effects if expressed in interstitial fibroblasts." (PMID 37910338, 2023). "Therefore, our results support the notion that PGE2 can override the tumor suppressor potential of the E-cadherin/CAV1 complex and that CAV1 released from the complex is phosphorylated on tyrosine-14 and promotes migration/invasion/metastasis." (PMID 38069269, 2023). "Moreover, PGE2 administration blocked the ability of the CAV1/E-cadherin complex to prevent tumor formation." (PMID 38069269, 2023). "Additionally, the high expression of caveolin-1 in tumor stroma, a significant component of caveolae, has been associated with improved responses to albumin-conjugated drugs in non-small cell lung cancer (NSCLC) patients." (PMID 38203730, 2023). "Cav1 is present in different cell types, tumor stages and locations, and its biological effects may vary." (PMID 37910338, 2023). "The obtained results indicate that miR-1207-5p, miR-1910-3p, and miR-940, the activity of which decreases with tumor progression, may be involved in the regulation of CAV1 expression." (PMID 37233761, 2023). "However, tumor heterogeneity leads to two-sided CAV1 expression; thus, the role of CAV1 as an oncogene or oncogenic factor is controversial." (PMID 37907864, 2023). "However, it was found that caveolin-1 can function as either a tumor suppressor or promoter, depending on the subtype of cancer in question." (PMID 37174125, 2023). "Caveolin-1 (Cav-1) is a functional membrane protein that plays a vital role in tumor metastasis." (PMID 37056561, 2023). "CAV1 is an integral membrane that works not only as a tumor promotor but also as a suppressor." (PMID 35719407, 2022). "Conversely, strong stromal CAV1 was associated with several favorable tumor characteristics: ER+ (Padj = 0.002), non-TNBC (Padj = 0.048), and lower frequency of histological grade III (Padj = 0.002)." (PMID 35660849, 2022). "Additionally, the sulfonate groups of IR783 enabled the enhanced tumor accumulation of IR783/BC NPs by CAV‐1‐mediated transcytosis." (PMID 36176605, 2022). "Some previous reports have demonstrated that CAV1 acts as both a tumor suppressor and an oncogene." (PMID 35495123, 2022). "Depending on the stage and type of tumor, the role of CAV-1 in cancer is ambiguous." (PMID 35053570, 2022). "CAV1’s prognostic impact depended on its localization, anthropometric, and tumor factors." (PMID 35660849, 2022). "Cav1 has also been demonstrated to enhance survival of tumor cells after RT." (PMID 36121548, 2022). "Overall, these results may lead to potential therapeutic strategies targeting Cav-1 and modulating the tumor microenvironment." (PMID 35992829, 2022). "Caveolin-1 (CAV1), a membrane-associated scaffolding protein with a dual role in tumor development and progression, has been implicated in the metabolic reprogramming of cells in the tumor environment." (PMID 35740528, 2022). "HPV type 31 enters keratinocytes via caveolae-dependent endocytosis, suggesting that CAV-1 may affect tumor development by controlling HPV infection in keratinocytes." (PMID 36532050, 2022). "Furthermore, Cav-1, a membrane-associated protein stabilized by FASN by palmitoylation, acts as a tumour-progressing factor, being involved in cancer-drug resistance along with P-glycoprotein (P-gp), a protein that pumps out drugs from targeted cells." (PMID 35334544, 2022). "Activated fibroblasts that were characterized by low CAV1 expression levels exhibited a more reactive tumor-promoting phenotype and induced resistance of PCa cells with differential CAV1 levels and of PCa cells with low endogenous CAV1 levels in a paracrine manner." (PMID 35155239, 2022). "Recently, CAV1 has been found to be actively involved in human tumor progression." (PMID 36233075, 2022).
tumor (continued). "Furthermore, we have recently shown that CAV-1, a tumor promoter sustaining rhabdomyosarcomagenesis, promotes radioresistance in RMS through increased oxidative stress protection and that RMS surviving to RT more efficiently detoxifies from ROS." (PMID 36248991, 2022). "The interplay between tumor size and stromal CAV1 is yet to be explored." (PMID 35660849, 2022). "The loss of stromal CAV1 in turn was accompanied with increased (stromal) TAGLN levels, an observation that was shown to account for a more activated and reactive nature of the respective tumor stroma." (PMID 35155239, 2022). "CAV1 (caveolin-1) is a key structural component of caveolae and plays an important role in a variety of cellular processes including cholesterol homeostasis, vesicle transport, and tumor progression." (PMID 35783270, 2022). "Notably, caveolin-1 has been shown to act as an anti-apoptotic and pro-apoptotic protein, both as a tumor promoter and a tumor suppressor." (PMID 35064107, 2022). "Lovastatin induced a significant reduction in CAV1 tumor levels and increased HER2 membrane levels." (PMID 35534471, 2022). "However, for some tumors, the up-regulation of caveolin-1 can affect the survival and growth of cancer cells and facilitate tumor progression." (PMID 35064107, 2022). "The increased metabolic potential of stromal fibroblasts compared to PCa cells further suggests that targeting fibroblasts and/or limiting fibroblast activation and induction of a CAF-like phenotype are absolute to inhibit the resistance-promoting CAV1-dependent signals of the tumor stroma." (PMID 35155239, 2022). "After RT, the presence of tumor cells that were permeable for propidium iodide, and thus clearly showed RT-­induced cell death, become prominent in LNCaP spheroids, an effect that was less pronounced in CAV1 WT LNCaP cells." (PMID 35155239, 2022). "For combined CAV1 status, the positive/not strong group was associated with unfavorable tumor characteristics (ER–, PR–, TNBC, histological grade III, and lower frequency of lobular-type tumors; all Padj ≤ 0.001)." (PMID 35660849, 2022). "The expression of CAV-1 in tumor tissues was detected by immunohistochemical staining." (PMID 36604141, 2022). "The mechanism of tumor growth inhibition mediated by CAV-1-expressing fibroblasts is unclear." (PMID 35410257, 2022). "Thus, targeting fibroblasts and/or limiting fibroblast activation, potentially by limiting the loss of stromal CAV1 seems to be absolute for inhibiting the resistance-promoting CAV1-dependent signals of the tumor stroma." (PMID 35155239, 2022). "Even in HCC, the function of CAV1 as a tumor suppressor or promoter is still under debate." (PMID 34178975, 2021). "Because of the constant overexpression of SYCP2, MYB and underexpression of CAV1 in HNSCC, these may be considered potential biomarkers of neoplasms associated to HPV, in addition to p16 and CCND1." (PMID 34830760, 2021). "We concluded that the expression of CAV1 correlated with the progression of the tumor." (PMID 35008571, 2021). "However, the role of Cav-1 in tumor development varies in different tumor types and is still subject of discussions." (PMID 33774714, 2021). "Further research could include a larger patient cohort to disentangle the function of the two different isoforms of Cav-1 as important structural components of caveolae formation and their effects on tumor progression." (PMID 33774714, 2021). "Whether these opposite effects may be related to the subcellular localization of CAV1 or the specific tumor cell-type, remains to be explored." (PMID 33718356, 2021). "Expression of Cav-1 in benign stroma was two-fold higher than in tumor stroma (p = 0.003)." (PMID 34813586, 2021).
tumor (continued). "Metabolic alterations are crucial for tumor cell survival, and in recent studies, caveolin-1 has been found to modulate cell metabolism with a focus on glycolysis (via hypoxia inducible factor 1α), mitochondrial bioenergetics, glutaminolysis, fatty acid metabolism, and autophagy in cancer cells." (PMID 33037799, 2021). "The differences found in the expression of the two isoforms of Cav-1 might account for the inhomogeneous data concerning the role of caveolin-1 in tumor progression." (PMID 33774714, 2021). "Previous studies have shown that hypoxia or high HIF-1α expression could directly (ZEBI, Snail, Twist, CAV-1) or indirectly (Notch, TGF-β, integrin-linked kinase) regulate EMT and the migration and invasion of various tumour cells." (PMID 34631221, 2021). "Moreover, in a study using mouse xenograft models, it was found that CAV-1 expression was positively correlated with the tumor sensitivity to nab-paclitaxel." (PMID 33816265, 2021). "However, our data from human HNSCC tissue arrays suggested that the expression of CAV1 correlated with the progression of tumor and was specifically stronger in advanced stages of cancer, especially in cancer cells invading neighboring stroma." (PMID 35008571, 2021). "Among the p16-negative tumors (n=26), tumors with low, moderate and high scores of CAV1 expressions within the tumor cells could be observed." (PMID 33868995, 2021). "Cav-1 expression in the tumor samples was as follows: 13 in 39 patients were caveolin expression negative, two out of 39 patients were caveolin expression positive 1+, 16 in 39 patients were caveolin expression positive 2+, and the remaining seven patients had 3+ positive caveolin expression." (PMID 34590611, 2021). "Similarly, increasing CAV1 levels in tumor epithelial cells were accompanied by with decreasing CAV1 levels within the tumor stroma as related to increasing tumor grades, an effect that was significant when considering p16-negative tumors only." (PMID 33868995, 2021). "Interestingly, a number of recent studies have investigated the role of Cav-1 in the tumor microenvironment, describing stromal Cav-1 (sCav-1) as a marker of the CAF phenotype in human breast cancer." (PMID 33531603, 2021). "In 11out of 39 patients Cav-1 expression was assessed in biopsies taken from metastatic sites, whereas in 28/39 patients caveolin expression was assessed in biopsies taken from the primary tumor." (PMID 34590611, 2021). "CAV-1 plays dual effects as an oncogene or as a tumor suppressor." (PMID 33935779, 2021). "Similarly, other studies demonstrated that downregulation of Cav-1 in fibroblasts induced a four-fold increase in tumor size." (PMID 34503536, 2021). "Using clinical and genomic databases (TCGA, CGGA and IVY) we examined the relationship between Cav-1 gene expression (including Cav-1 protein spatial distribution within the tumour) and known clinical pathological parameters of the GB tumour and the survival probability in a cohort GB patients." (PMID 34490102, 2021). "We then examined the survival of patients by the tumour level of Cav-1 but across GB subtypes." (PMID 34490102, 2021). "Using clinical and genomic databases we examined the relationship between tumour Cav-1 gene expression (including its spatial distribution) and clinical pathological parameters of the GB tumour and survival probability in a TCGA cohort (n=155) and CGGA cohort (n=220) of GB patients." (PMID 34490102, 2021). "OvCa stroma showed Cav-1 downregulation compared to tumor epithelium with IHC (p = 1.2x10-24)." (PMID 34813586, 2021). "CAV-1 expression is positively correlated with disease stage, tumor grade and metastatic potential." (PMID 34631790, 2021). "Furthermore, the different Cav-1 isoforms tended to be differently expressed in different tumor stages." (PMID 33774714, 2021).